PIK3CA (phosphatidylinositol-4,5-bisphosphate 3-kinase catalytic subunit alpha)
Diseases named in the same sentence as PIK3CA in open-access papers (continued):
Sharing a sentence is not in itself a finding about the gene and the disease.
breast cancer (continued). "•PIK3CA, the most frequently mutated gene in breast cancer, influences aggressive behaviour in TNBC and promotes tumor tropism." (PMID 39369580, 2024). "Asian breast cancer patients harbouring wildtype PIK3CA were significantly associated with better pCR outcomes when treated with TA in the neoadjuvant setting (p=0.001)." (PMID 38576013, 2024). "In a research of Twenty-nine people with preliminary breast cancer, the effectiveness of ptDNA (plasma Tumor DNA)/ddPCR for identifying PIK3CA mutations was established with 93.3% sensitivity and 100% specificity." (PMID 38753424, 2024). "PIK3CA mutations are a known oncogenic driver in breast cancer and drive therapeutic resistance in multiple HER2-targeted therapies." (PMID 38650031, 2024). "PIK3CA is the most frequently mutated gene in canine mammary carcinomas, and mutations homologous to the PIK3CA hotspot mutations found in breast cancer in humans have been identified, specifically PIK3CA p.H1047R and p.E545K." (PMID 38787171, 2024). "The results of our study contribute to the growing body of evidence regarding the role of PIK3CA mutations in early breast cancer prognosis and treatment response." (PMID 39742376, 2024). "It is currently being investigated in several trials including phase III trial of PIK3CA-mutated HER2-positive advanced breast cancer patients in combination with anti-HER2 and endocrine therapy (NCT05894239)." (PMID 38396649, 2024). "In HER2+ breast cancers, approximately one‐third of patients had Tier R1 PIK3CA mutations, which were linked to resistance to anti‐HER2 therapy." (PMID 38895905, 2024). "In the neoadjuvant setting, molecular subtypes (HER2E and TNBC), biomarkers (ER, PR, HER2, HR, Ki-67, nm23-H1, CK5/6, and Tau), and gene (PIK3CA) are associated with increased pCR rates in Asian breast cancer patients." (PMID 38576013, 2024). "The detection of the PIK3CA variant is important for breast cancer because the PIK3CA variant can result in resistance to HER2-targeted therapies." (PMID 39201281, 2024). "PacBio sequencing was used to phase the allelic configuration of PIK3CA mutations in breast cancer patients with double mutations in PIK3CA." (PMID 38610953, 2024). "Somatic mutations in PIK3CA gene were associated with shorter survival in glioma, but had an opposite effect in breast cancer." (PMID 39277826, 2024). "In this TNBC population, tumor PIK3CA mutations, excluding CNAs, had a prevalence of 13.5%, which aligns with previous findings that show PIK3CA is frequently mutated in breast cancer and is potentially an actionable target in the advanced setting." (PMID 38869771, 2024). "PIK3CA gene mutations, which are often present in advanced HR+ breast cancer, can be targeted by alpelisib." (PMID 39596311, 2024). "Alpelisib, a PI3Kα inhibitor, is currently used as a therapeutic drug for ER-positive, HER2-negative, PIK3CA-mutated breast cancer." (PMID 38164185, 2024). "The catalytic domain P110 has three isoforms (α, β, and δ); p110α is encoded by PIK3CA, whose mutations have been reported in around 30–40% of breast cancer." (PMID 38337803, 2024). "NF1 and PIK3CA gene mutations were reported to have a risk prognostic effect in breast cancer, while this analysis also showed association in glioma and lung cancers." (PMID 39277826, 2024). "Among them, the inhibitor BYL719, which targets p110α specifically, has demonstrated increased efficacy in various breast cancer cell lines with mutations in PIK3CA and HER2 positivity." (PMID 38875362, 2024). "In vitro studies further demonstrate increased trastuzumab resistance in Her2+ breast cancer cells with PIK3CA-activating mutations." (PMID 38255807, 2024).
breast cancer (continued). "One of these such genes, PIK3CA, encodes the catalytic subunit of the PI 3-kinase α and is frequently mutated in various carcinomas, and especially in breast cancer, where it is mutated in about one third of the cases." (PMID 38786098, 2024). "We have recently shown that comprehensive liquid biopsy analysis including the analysis of PIK3CA mutations in CTCs and ctDNA is a very informative tool for the early detection of minimal residual disease in breast cancer." (PMID 39711963, 2024). "Alpelisib selectively inhibits the p110α subunit of PI3Kα and is approved for treating breast cancers with PIK3CA mutations." (PMID 39768828, 2024). "Clinical studies of the use of inavolisib in HER2+ breast cancer, particularly in patients with PIK3CA mutations, have gradually been initiated over the past two years." (PMID 39769140, 2024). "In the present study, we found that PIK3CA mutations were the most commonly observed alternations in Taiwanese patients with breast cancer, particularly in HR + HER2− breast tumors, accounting for 43.1% of cases." (PMID 38895905, 2024). "PIK3CA mutations occur frequently in exons 9 and 20, notably at positions H1047R, E545K, and E542K, which account for 70–80% of PIK3CA mutated cases in breast cancer." (PMID 39197004, 2024). "Methods currently used to detect PIK3CA mutations in breast cancer patients include Sanger sequencing, PCR-RFLP, next-generation sequencing (NGS), and digital PCR (dPCR)." (PMID 39070168, 2024). "Initial research on multi‐PIK3CA mutations has predominantly focused on breast cancer; however, the frequency, mutation sites, co‐occurrence with other genomic alterations, and their links to mutational signatures in other cancer types are not well understood." (PMID 39054873, 2024). "Forty-percent of patients with HR + HER2- breast cancer harbor activating mutations in the PIK3CA gene, inducing hyperactivation of the alpha-isoform (p110α) of phosphatidylinositol 3-kinase (PI3K)." (PMID 38584192, 2024). "This regimen elucidated a substantial enhancement in PFS among patients afflicted by advanced breast cancer characterized by PIK3CA, HR-positive, and HER2-negative mutations, in contrast to the administration of Fulvestrant as a monotherapy." (PMID 38474678, 2024). "Beyond breast cancer, PIK3CA mutation detection is also very important in other types of cancer like lung, colorectal, anal squamous cell carcinoma and pancreatic cancer." (PMID 39711963, 2024). "The current treatment recently approved by the US FDA for breast cancer with PIK3CA mutation includes an oral medication Alpelisib acting as PI3K Alpha-Selective Inhibitor." (PMID 38576013, 2024). "The combination of alpelisib and capecitabine demonstrated sustained clinical activity in some breast cancer patients with PIK3CA mutations." (PMID 39070139, 2024). "Alpelisib, a selective PI3Kα inhibitor, has demonstrated a notable efficacy in targeting PIK3CA-mutated tumors, a significant genetic subgroup within breast cancer." (PMID 39743996, 2024). "PI3Kα inhibitor, alpelisib, in combination with the ET fulvestrant, is approved for PIK3CA-mutated, advanced HR+ breast cancer." (PMID 39409880, 2024). "Alpelisib has been approved in combination with fulvestrant for treating PIK3CA-mutated breast cancer patients, based on the SOLAR-1 phase III trial results." (PMID 39769028, 2024). "Our aim was to examine the association between and impact of PIK3CA mutation status on disease-free survival (DFS) in HR+/HER2− early breast cancer patients." (PMID 39742376, 2024). "Studies like the STIC-CTC and DETECT-III trials emphasize the predictive value of CTC quantity and characteristics and genomic analysis of CTCs has revealed mutations in genes such as AKT1 and PIK3CA, crucial for targeted breast cancer treatments." (PMID 39304879, 2024).
breast cancer (continued). "This study provides a single-cell atlas of breast tissues of BRCA1/2 mutation carriers and demonstrates that aberrant signaling due to BRCA1/2 mutations is sufficient to initiate breast cancer by mutant PIK3CA." (PMID 38059556, 2024). "For example, the PIK3CA H1047R mutation antagonizes lung metastases in a mouse model of ErbB2-induced breast cancer." (PMID 38786098, 2024). "The three main PIK3CA hotspot mutations, exon 9 p.E545K and p.E542K and exon 20 p.H1047R, are detected approximately in 40% of hormone receptor positive (HR+) breast cancer, mainly in the helical and kinase domains of the PIK3CA gene." (PMID 39711963, 2024). "Activating mutations in PIK3CA were the most prevalent oncogenic events observed in HR + HER2− breast cancer cases across various ethnic backgrounds." (PMID 38895905, 2024). "Specifically, mutations in PIK3CA resulted in poor outcomes in metastatic breast cancer patients and resistance to chemotherapy; the loss of PIK3CA suppressed cancer cell growth and migration in malignancies." (PMID 38179473, 2024). "Fourteen women diagnosed with advanced HR+/HER2– breast cancer carrying a PIK3CA mutation who initiated therapy with Alpelisib were included in the analysis." (PMID 38963515, 2024). "Alpelisib, an alpha‐selective phosphoinositide 3‐kinase (PI3K) inhibitor, gained approval for the treatment of HR + HER2− breast cancers with PIK3CA mutations, as identified through the US FDA‐approved therascreen® PIK3CA PCR companion diagnostic (CDx) test." (PMID 38895905, 2024). "PIK3CA missense variants leading to an oncogene gain of function is a classical feature of luminal breast cancer in both young and elderly patients." (PMID 39208653, 2024). "Targeted PI3K inhibition for patients with PIK3CA mutations has been explored as a pathway to overcome ET resistance in HR+breast cancers." (PMID 38439079, 2024). "The frequency of PIK3CA mutations among all sequenced patients was 34% (12/35), similar to that seen in other studies of unselected metastatic and early-stage breast cancer patients (cBioPortal)." (PMID 38650031, 2024). "•Current clinical trials assess combinations of hormone therapy and dual inhibitors for targeting the PIK3CA-mutated breast cancer subtypes." (PMID 39369580, 2024). "Studies in breast cancer suggest that PIK3CA mutations are driver alterations and early events in the malignant transformation of these tumors." (PMID 39684756, 2024). "Here, we aim to assess the mutational status of PIK3CA in metastatic breast cancer tissues from Chilean patients and describe their clinicopathological characteristics and survival outcomes." (PMID 39596311, 2024). "Approximately 40% of HR+/HER2- breast cancers have activating mutations in the PIK3CA gene, leading to the hyperactivation of the catalytic subunit p110α of phosphatidylinositol 3-kinase (PI3K)." (PMID 38256428, 2024). "Based on the positive results of SOLAR-1, the FDA approved alpelisib in combination with fulvestrant for advanced HR+/HER2- breast cancer with PIK3CA mutations in postmenopausal women." (PMID 38256428, 2024). "A 44% of human breast cancers have been reported to bear mutations in PIK3CA (35.8% in cBioportal.org) of mainly Luminal A subtype." (PMID 38987766, 2024). "Studies have found that mutations in PIK3CA can induce resistance to trastuzumab or combination anti-HER2 therapies in breast cancer cells in vitro." (PMID 39769140, 2024).
breast cancer (continued). "Approximately 80% of the PIK3CA mutations cluster within three hotspots in the coding sequence: E542K (~ 4% of human breast cancer) and E545K (~ 6%) within the helical domain; and H1047R (~ 15%) within the kinase domain of p110 α12–14." (PMID 39462049, 2024). "Evidence suggests that patients with relapsed or refractory indolent lymphoma treated with PI3K inhibitor exhibit an ORR of 59%, also significantly prolonged progression-free survival for patients harbor PIK3CA mutation in advanced breast cancer." (PMID 39068158, 2024). "And alpelisib, phosphoinositide 3-kinase inhibitor, shows efficacy in PIK3CA-mutated recurrent breast cancer patients." (PMID 38229073, 2024). "PIK3CA-mutated mammary tumour organoid lines have also been shown to be more sensitive to alpelisib than wild-type organoid lines." (PMID 38787171, 2024). "The overall aim of this study was to investigate PIK3CA mutations in endocrine-resistant breast cancer tumors to improve our understanding of the endocrine resistance mechanism." (PMID 38822093, 2024). "Alpelisib (BYL719) is a selective inhibitor of the PI3K α isoform and has been extensively studied in breast cancer patients with PIK3CA mutations." (PMID 39769140, 2024). "Alpelisib, a new drug used to treat phosphatidylinositol-4,5-bisphosphate 3-kinase catalytic subunit alpha mutated breast cancer, is reported to cause DKA as a rare adverse effect." (PMID 38524964, 2024). "In conclusion, we provide valuable information into the molecular landscape of advanced HR+ HER2− breast cancer in Chile, offering one of the first in-depth analyses of PIK3CA mutations in our population." (PMID 39596311, 2024). "Previous studies have reported somatic mutations and amplification of the PIK3CA gene in various human cancers, including breast cancer, which is particularly prevalent among women." (PMID 39541191, 2024). "PIK3CA mutations are particularly common in early breast cancer, present in up to 47% of hormone receptor-positive (HR+)/HER2– luminal A tumors, 33% of HR+/HER2+ luminal B tumors, 39% of HER2-enriched tumors, and 8–25% of basal-like or triple-negative tumors." (PMID 39850811, 2024). "Mutations in the PI3K gene, particularly PIK3CA mutations, have been linked to breast cancer and solid tumors." (PMID 38811791, 2024). "It is noted that there is a high incidence of discrepancy in the PIK3CA variant between primary breast cancer tumors and metastases, hence the detection of metastatic lesions is essential." (PMID 39201281, 2024). "The breast cancer cell lines E545K and H1047R, which harbor PIK3CA mutations, exhibited anoikis resistance and promoted tumorigenicity." (PMID 38785271, 2024). "As for another important breast cancer mutant genotype, the PIK3CA mutation, Alpelisib/Fulvestrant is the recommended treatment according to NCCN guidelines." (PMID 38212842, 2024). "These include the Cobas EGFR mutation test V2, which can identify EGFR mutations in non-small cell lung cancer, and the Therascreen PIK3CA RGQ PCR kit, which can identify PIK3CA mutations in breast cancer." (PMID 39219215, 2024). "Quick, reliable and inexpensive identification of PIK3CA mutations is crucial for determining which breast cancer patients will benefit from these specific treatments." (PMID 39711963, 2024). "The PI3K inhibitor alpelisib has been approved by the US Food and Drug Administration and is in the clinical setting in Sweden offered to patients with advanced breast cancer harboring a PIK3CA mutation." (PMID 38822093, 2024). "Constitutional mutations of the PIK3CA gene appear to increase the risk of breast cancer, gynecologic tumors, and thyroid pathology." (PMID 39336800, 2024). "The response to neoadjuvant chemotherapy in HER2-positive breast cancer can also vary based on PIK3CA mutations and hormone receptor status." (PMID 38256428, 2024).
breast cancer (continued). "Evidence for the applicability of our workflow in breast cancer was used to analyze the two most common PIK3CA mutations in breast cancer to identify distinct molecular differences that impact downstream signaling, chromatin accessibility, and gene expression." (PMID 38802751, 2024). "PIK3CA mutations are present in 20% to 50% of patients with breast cancer, including 35% of hormone receptor-positive patients." (PMID 39544302, 2024). "In brief, alpelisib, a PI3K inhibitor, has proven effective for HR+/HER2- breast cancer with PIK3CA mutations, as shown in the SOLAR-1 trial." (PMID 38256428, 2024). "The FDA has approved the use of therascreen in tumor tissue and plasma and FoundationOne CDx in tissue samples for the detection of PIK3CA mutations in breast cancer patients." (PMID 39769140, 2024). "In our present study, we identified three patients with HR + HER2− breast cancer harboring double oncogenic PIK3CA mutations using NGS‐based techniques and one patient using PCR‐based methods." (PMID 38895905, 2024). "Mutations in the phosphatidylinositol 4,5-bisphosphate 3-kinase catalytic subunit alpha (PIK3CA) gene are highly prevalent (30–40%) in HR+/HER2− advanced breast cancer." (PMID 39742376, 2024). "In conclusion, this study proposes a fast and highly sensitive biosensor for the detection of a key breast cancer marker, the PIK3CA-H1047R variant." (PMID 39070168, 2024). "PIK3CA mutations in breast carcinoma were reported to be a favorable prognostic factor, associated with a low histologic grade, advanced age at diagnosis, and the absence of lymph node invasion, with small tumor size, and with a low proliferation index (Ki67)." (PMID 38893129, 2024). "Alteration of the PI3K pathway and PIK3CA mutation plays a key role in tumor tropism and metastasis in breast cancer (BC)." (PMID 39369580, 2024). "One of these inhibitors, BYL719, also known as Alpelisib, is recommended for the treatment of mammary carcinomas, where PI 3-kinase activity is elevated due to PIK3CA mutations." (PMID 38786098, 2024). "PIK3CA is the most frequently mutated gene in breast cancer (BC), yet its relevance to BC prognosis remains controversial." (PMID 38466449, 2024). "Overall, our data support the clinical development of alpelisib as part of therapeutic strategies for patients with HER2+ breast cancer harboring PIK3CA activating mutations." (PMID 37469415, 2023). "In breast cancer, identification of PIK3CA mutations informs treatment with the PI3Kα-specific inhibitor alpelisib in combination with fulvestrant as a second-line therapy for advanced disease." (PMID 37958763, 2023). "We found seven significantly mutated genes (SMGs) whose mutation rates were significantly higher than the background mutation rate in canine mammary tumors (CMTs) and reported that the PIK3CA gene was the most frequently mutated in CMT (45%)." (PMID 37009802, 2023). "The hotspot mutations in canine mammary gland tumors were an exact match for previously reported hotspot PIK3CA mutations in human breast cancer with a prevalence of ~30%31." (PMID 37009802, 2023). "No alterations in key actionable genes including ERBB2 (HER2), NTRK fusions, or PIK3CA mutations were identified in breast cancer patients." (PMID 35648382, 2023). "Our findings support the use of an alpha-selective PI3K inhibitor to overcome the therapeutic limitations associated with single or dual HER2 blockade in PIK3CA-mutant HER2+ breast cancer." (PMID 37469415, 2023). "In conclusion, the present study demonstrated that HER2-positive breast cancers with activating mutations in PIK3CA are less likely to benefit from pyrotinib combined with trastuzumab neoadjuvant therapy." (PMID 36323880, 2023). "This is a finding unique to endometrial cancers, as numerous other studies of blood, brain, and breast cancers have deemed PIK3CA and PTEN mutations to be mutually exclusive." (PMID 37465112, 2023).